IDH2 (isocitrate dehydrogenase (NADP(+)) 2)
Diseases named in the same sentence as IDH2 in open-access papers (continued):
Sharing a sentence is not in itself a finding about the gene and the disease.
cancer (continued). "In last decades, mutations identified in IDH1 and IDH2, and a few other metabolic genes, such as succinate dehydrogenase (SDH) and fumarate hydratase (FH), have provided compelling evidence for metabolic alteration in human cancer development and progression." (PMID 37296846, 2023). "Various cancers differ in the expression of IDH2, which may be related to the cancer type and staging." (PMID 36497259, 2022). "We also examined the critical protein IDH2 in cancer metabolism." (PMID 36304962, 2022). "The study also suggested that IDH2 inhibition could transform cancer treatment from cytotoxic to precision therapy and fundamentally change the cancer treatment landscape." (PMID 36497259, 2022). "Indeed, when we inhibit oxidative phosphorylation by targeting IDH2, resistance is impaired, providing more direct evidence that this metabolic switch is important for cancer development." (PMID 36153371, 2022). "Mutations in IDH2 are also apparent in GBM and other cancers." (PMID 34050894, 2022). "TCA cycle genes, encoding isocitrate dehydrogenase (IDH1 and IDH2), fumarate hydratase (FH), and succinate dehydrogenase (SDHA, SDHB, SDHC, SDHD, and SDHAF2) are mutated both germinally and somatically in a number of human cancers." (PMID 33572577, 2021). "This metabolic deregulation may partially contribute to development of human cancer carrying oncogenic IDH1 and IDH2 mutations." (PMID 34516556, 2021). "The low frequencies of IDH1 and IDH2 mutations in human cancer were confirmed with MSK_Impact; the overall frequencies of IDH1 and IDH2 alterations were 3% and <1%, respectively; and IDH1 and IDH2 hotspot mutations were 2% and 0.3% (or 260 and 31), respectively." (PMID 34440884, 2021). "In conclusion, the development of oral, potent, small molecule and mutant specific IDH1 and IDH2 inhibitors represents an early success story of the cancer genome-sequencing era, and signifies an important advance for AML therapy in the era of personalized therapeutics." (PMID 34083508, 2021). "Nevertheless, a prominent status of the IDH1 and IDH2 mutations has never been undertaken particularly within a large number of different human cancer samples." (PMID 35996504, 2021). "Furthermore, various mutations in Krebs cycle enzymes, including succinate dehydrogenase (SDH), fumarate hydratase (FH), and isocitrate dehydrogenase 1 (IDH1) and 2 (IDH2), are described in cancer cells." (PMID 34445360, 2021). "Meanwhile, down‐regulation of IDH2 sensitizes cancer cells to erastin‐induced ferroptosis, which might become a new strategy in cancer chemotherapy." (PMID 33455080, 2021). "Human cancer samples (solid tumors) analyzed for IDH1 and IDH2 gene mutations." (PMID 35996504, 2021). "The differential diagnosis of poorly differentiated SNSCC is challenging and includes: SNUC (including those characterized by molecular identifiers, such as IDH2-mutant SNUC, SMARCA4-deficient carcinoma, and SMARCB1/INI1-deficient carcinoma), NECs, and adenoid cystic carcinoma." (PMID 34200193, 2021). "The newly identified lysine residues might apply in regulation of IDH2 function in response to metabolic perturbations occurring in cancer cells, such as glucose-free conditions." (PMID 32457458, 2020). "This interaction of cancer cells and CAFs was observed for several CRC cell lines and associated with a reduced expression of the TCA enzyme IDH2, the induction of the glycolytic enzyme PKM2 and GAPDH expression, which increased autophagy in CAFs mediated by ROS signaling." (PMID 32610612, 2020). "This study highlighted the important role of IDH2 also in preventing cancer formation." (PMID 31010244, 2019). "The function of IDH2 in cancer has been relatively well documented." (PMID 31516386, 2019). "Numerous reports recognized aberrant IDH2 expression in cancers." (PMID 31010244, 2019). "Cancer-related mutations in IDH1 and IDH2 are mostly heterozygous and are always hotspot mutations involving arginine residues R132 in IDH1 and R140 or R172 in IDH2." (PMID 31139406, 2019).
cancer (continued). "Further, siRNA knockdown studies of IDH1 and IDH2 resulted in slow a growth of cancer cells." (PMID 29439493, 2018). "Further, the study will also be needed to determine whether serum IDH2 is an accurate biomarker for other cancer types or is specific for NSCLC." (PMID 29465809, 2018). "There is a renewed interest in the area of cancer metabolism with metabolic reprogramming coined as a hallmark of cancer based on the discovery of mutations and alterations in IDH1 and IDH2 along with succinate dehydrogenase (SDH), fumarate hydratase (FH), and pyruvate kinase M2 (PKM2)." (PMID 30024920, 2018). "This mitochondrial NADPH shuttle system implies that NADPH-producing pathways in mitochondria could partially contribute to cytosolic NADPH pool maintenance, mostly in cancer cells using IDH2 to sustain reductive carboxylation." (PMID 28649560, 2017). "Given the emergence of loss of IDH2 as an important event in various malignancies, these results suggest that cancer cells overexpressing WEE1 may epigenetically suppress the expression of IDH2 gene to prevent the formation of 5-hmC." (PMID 29290954, 2017). "It is worth mentioning here that, theoretically, decreasing intracellular 2KG level might have a deleterious effect on the 2KG requiring dioxygenases that are already inhibited in IDH1 R132 and IDH2 R172 mutant cancer." (PMID 28785398, 2017). "Cancer cells with ablated expression of the mitochondrial isoform IDH2, had diminished capacity to form tumors when grafted into mice as compared with cancer cells where IDH2 expression was retained." (PMID 26791262, 2016). "The cancer-associated mutant IDH1 or IDH2 exclusively produces D-2-HG, but not L-2-HG, both of which are byproducts of normal mitochondrial metabolism." (PMID 25825982, 2015). "Thus, Sp1-mediated overexpression of the wild-type IDH2 gene in response to hypoxia potentially contributes to the radioresistance of cancer cells." (PMID 26703734, 2015). "Intriguingly, our simple correlation of clinical variables with intron retention suggested that mutations affecting factors not canonically involved in RNA processing, such as IDH1 and IDH2, may contribute to splicing dysregulation in cancer." (PMID 26113877, 2015). "IDH1- and IDH2-mutant cancer cells aberrantly accumulate D2-hydroxyglutarate (D2-HG)." (PMID 26178471, 2015). "This could be a consequence of genetic alterations in enzymes regulating epigenetic patterns, such as gene mutations found in human myeloid malignancies, including DNMT3a, TET2, IDH1, IDH2, EZH2, or ASXL1." (PMID 24944583, 2014). "Hence, we propose the TCM compounds, precatorine and abrine, as potential candidates as lead compounds for further study in drug development process with the IDH2 R140Q mutant protein against cancer." (PMID 24995286, 2014). "This may be cancer-specific though, as mutant IDH2 alone was recently shown to be sufficient to induce sarcoma formation in mice, at least in one model system." (PMID 24622842, 2014). "Since binding to IDH1-WT may be an important function for IDH1 R132 mutants in cancer, we hypothesized that IDH2 R172 mutants may localize outside the mitochondria and also bind IDH1-WT." (PMID 21326614, 2011).
cancer (continued). "Indeed, we found that several cancer-related genes were recurrently hit by somatic variants in multiple non-cancer blood samples, including three previously reported CHIP genes: IGLL5, RAD21, and IDH2." (PMID 41505106, 2026). "IDH2 has been shown to reduce and convert α‐ketoglutarate to citric acid, a metabolic pathway that increases in factors such as impaired mitochondrial respiration, hypoxic environments, or cancer cell metabolism, and is considered a key enzyme in the rTCA cycle." (PMID 41456904, 2026). "Additionally, these strategies may also be combined with drugs targeting cancer-specific mutations, including mutated IDH1 and IDH2, which are also known contributors of TME-induced immunosuppression." (PMID 41235226, 2025). "Additionally, enhancing the effectiveness of CAR T cell therapies through IDH2 inhibition could revolutionize cancer immunotherapy." (PMID 39409901, 2024). "However, the effect of IDH2-deficient macrophages on cancer progression has not been extensively researched." (PMID 39256649, 2024). "Moreover, the p-AMPK and p-STAT3 levels and VEGF expression were also reduced in TAMs of IDH2-deficient mice, indicating that most IDH2-deficient TAMs did not differentiate into M2 macrophages and that cancer progression was inhibited in IDH2-deficient mice." (PMID 39256649, 2024). "Furthermore, IDH2-deficient macrophages failed to promote cancer cell growth and epithelial–mesenchymal transition (EMT) in vitro and in vivo." (PMID 39256649, 2024). "Fumarate and succinate antagonize the roles of α-KG In addition to IDH1 and IDH2, germinal and somatic mutations of fumarate hydratase (FH) and succinate dehydrogenases (SDHA, SDHB, SDHC, SDHD, and SDHAF2), encoding FH and SDH enzymes, are common in a number of human cancers." (PMID 34050894, 2022). "This approach could also be extended to treat other cancers harboring an IDH2 mutation where targeted therapies have not yet been successful." (PMID 34489470, 2021). "Similar pseudohypoxic conditions may also prevail due to the accumulation of competitive antagonist 2-hydroxyglutarate (D-2HG) in IDH2 mutant cancers and in acidic pH, which enhances the production of L-2HG via the noncanonical activity of lactate dehydrogenase." (PMID 34829708, 2021). "The role of mitochondria in cancer development is primarily focused on mutations in genes in TCA cycle enzymes, namely succinate dehydrogenase (SDH), fumarate hydratase (FH) and isocitrate dehydrogenase 2 (IDH2), leading to the accumulation of succinate, fumarate and 2-hydroxyglycerate (2HG)." (PMID 34829708, 2021). "Therefore, the disruption of the normal functions of IDH1 and IDH2 may significantly affect the cellular redox balance and result in cancer cell growth dysfunction." (PMID 29661250, 2018). "Interestingly, in vitro studies indicate that cancer cells supplement deficiency of acetyl-coA for lipid biogenesis through reductive glutamine metabolism mediated by cytoplasmic and/or mitochondrial IDH1 and IDH2, respectively." (PMID 27682873, 2017). "In addition to the downregulated expression of TET genes, it was reported that decreased 5-hmC expression in malignant tumors could be caused by mutations in the TET, IDH1 or IDH2 genes." (PMID 27050164, 2016). "Ongoing clinical trials are testing the anticancer activity of specific inhibitors of IDH1 and IDH2 mutant enzymes and a positive outcome would support the concept of oncometabolites, thereby providing a productive new example of targeted therapy against cancer metabolism." (PMID 27635066, 2016). "In different cancer types, including HCC, a decreased level of 5hmC was shown to be caused by either reduced expression of the TET proteins or by inhibition of their activity by toxic metabolite α-hydroxyglutarate which is produced by gain-on-function mutant isocitrate dehydrogenases IDH1 or IDH2." (PMID 25918251, 2015). "Moreover, knocking down IDH2 impaired cell proliferation in cancer cells." (PMID 26437434, 2015).
cancer (continued). "Mutation of these genes in cancer leads to a buildup of their substrates; fumarate and succinate in the case of FH and SDH mutations, or conversion of their regular substrate to a new “oncometabolite” in the case of mutant IDH1/IDH2 converting isocitrate to 2-hydroxyglutarate." (PMID 24350057, 2013). "The relative importance of either dominant negative activity or 2HG-producing catalytic activity for the IDH1 and IDH2 mutants in cancer is unclear, and the mechanism by which either of these gained functions may contribute to cancer pathogenesis remains unknown." (PMID 21326614, 2011). "Isocitrate dehydrogenase 2 (IDH2), an enzyme involved in the TCA cycle, reportedly promotes cancer progression." (PMID 39256649, 2024). "The level of α-KG was substantially lower in the non-cancer cells (MCF10A), which also exhibited lower expression of IDH2." (PMID 38658533, 2024). "Interestingly, computational analysis of the TCGA pan-cancer data characterized both gene expression and DNA methylation as the most effective predictors of the somatic mutation state, as previously demonstrated with the oncogenic mutations of the IDH1 and IDH2 genes in cancer." (PMID 38067407, 2023). "Additionally, three other NADBPs, which mutations are implicated in cancer, were found in the catalogue of FDA approved targets, namely, 5-aminoimidazole-4-carboxamide ribonucleotide formyltransferase/IMP cyclohydrolase (ATIC), androgen receptor (AR) and isocitrate dehydrogenase 2 (IDH2)." (PMID 36880517, 2023). "Inhibition of IDH2 leads to an abnormal accumulation of ROS, likely due to suppression of the IDH2-mediated NADPH generation, and renders the cancer cells more vulnerable to ROS stress induced by cisplatin." (PMID 36831011, 2023). "In cancer cells, IDH1- or IDH2-mediated carboxylation of α-KG to citrate is crucial for cell growth and viability under hypoxia." (PMID 35762591, 2022). "Cancer related chromosomal translocations/deletions involving Chromosome region 2q34 (location of IDH1) and Chromosome region 15q26.1 (location of IDH2) are relatively rare." (PMID 34854890, 2021). "Some of them have been reported as biomarkers in other types of cancers, such as GSTK1, IDH2, CAVIN3, HMGCS2, and ACOX1." (PMID 34557266, 2021). "On the contrary, Sirt3 overexpression increases IDH2 and SOD2 activities, decreases ROS levels, glucose consumption, and lactate production, inhibiting cancer cells proliferation." (PMID 31010244, 2019). "IDH2 and PDK3 have been shown to positively regulate the proliferation and tumorigenesis of various cancer cells." (PMID 29772705, 2018). "The role of IDH2 and GDH1 appears to be cancer type-dependent and contributes to NADPH accumulation in mitochondria only in the context of glutamine anaplerosis of forward TCA cycle." (PMID 28649560, 2017). "Mutations in isocitrate dehydrogenase enzymes IDH1 (cytosolic) and IDH2 (mitochondrial) are highly frequent in glioma and AML, though rare in other cancers." (PMID 28373964, 2017). "Each subpanel corresponds to one gene (ATRX, OLIG2, MGMT, and IDH2) and displays its expression levels in tumors (red) and normal tissues (blue) across multiple cancer types." (PMID 40282990, 2025). "In our study, we found a significantly lower IDH2 expression in sp-FL tumors compared with np-FL tumors, which is in contrast to many studies which have shown that overexpression of proteins in the IDH family supports cancer growth." (PMID 39409899, 2024).
cancer (continued). "Then, regardless of co-culture with cancer cells, the mitochondrial membrane potential reduced in IDH2-/- macrophages." (PMID 39256649, 2024). "While mutated IDH1 and IDH2 are cancer-driver genes through the production of 2-HG and its impact on the epigenome, IDH3 has not been characterized as such in cancer." (PMID 37601653, 2023). "IDH3 is not as well characterized as IDH1 and IDH2 in the context of cancer and other diseases; however, more recent studies implicate aberrant expression of IDH3—especially the alpha subunit—in malignancy." (PMID 36549590, 2023). "Cancer types that displayed the largest differences between groups were LGG (IDH1 1% in the low- versus 95% in the high-methylation group), GBM (IDH1 0% versus 88%), LAML (IDH1 6% versus 56%; IDH2 3% versus 44%) and KIRC (SETD2 0% versus 36%)." (PMID 35134107, 2022). "Moreover, eight axes (e.g., OIP5-AS1/miR-124-5p/IDH2) are involved in key pathways, such as Wnt/b-catenin, E2F1, TGF-β, SMAD, ERK/MAPK, HIF-1α, Notch, PI3K/Akt signaling, and cancer cell stemness." (PMID 36362406, 2022). "Multiple IDH1 and IDH2 inhibitors are reported, though only one IDH1 inhibitor (ivosidenib) and one IDH2 inhibitor (enasidenib) have been approved for clinical use, i.e. for acute myeloid leukaemia (AML) treatment where the cancer cells make an IDH variant." (PMID 35970853, 2022). "Thus, IDH2 may have an important role in cell proliferation, which is a perquisite step of the invasion and metastatic process, which can lead to the development of invasive cancer from a pre-invasive lesion, and for development of LVI and hence distant metastasis." (PMID 31599393, 2020). "Moreover, the key regulatory enzymes in the isocitrate dehydrogenase (IDH) family, including IDH1, IDH2, and IDH3A, played differential in the two cancer types." (PMID 32127786, 2020). "Here, we summarize studies reporting on aberrant IDH1, IDH2, and IDH3 expressions in cancers." (PMID 31010244, 2019). "To date, no study has reported cancer-associated mutations in IDH3, although IDH3 has a similar function as that of IDH1 and IDH2." (PMID 31660152, 2019). "These include specific inhibitors of cancer-specific mutant isocitrate dehydrogenase (IDH 1 and/or IDH2), of the monocarboxylate transporter, critical for cancer cell nourishment using lactate, of the pyruvate dehydrogenase complex or of the mitochondrial complex I." (PMID 29713632, 2018). "CD44+/CD117+ cancer stem cells isolated from the peritoneal fluid of HGSOC patients that had the ability to form tumors in mice, showed decreased levels of pyruvate dehydrogenase kinase (PDHK1) and increased expression of isocitrate dehydrogenase (IDH2)." (PMID 30231564, 2018). "Further, this decrease in IDH2 gene expression correlated with reduced 5-hmC levels, suggesting that the overexpression of WEE1 in cancer cells may suppress the expression of IDH2, leading to decreased 5-hmC levels." (PMID 29290954, 2017). "Reductive carboxylation of 2-oxoglutarate by IDH2 (in the reverse Krebs cycle direction), which consumes NADPH, may follow glutaminolysis of glutamine to 2-oxoglutarate in cancer cells." (PMID 22675360, 2012). "The importance of this neomorphic IDH2 activity for the cancer phenotype is valid even without consideration of d-2-hydroxyglutarate interference with epigenetics and the HIF pathway, because IDH2 depletes 2OG from the Krebs cycle." (PMID 22675360, 2012). "However, the majority of human cancers do not contain TET1, TET2, TET3, IDH1, or IDH2 mutations and, still show a reduced 5hmC compared to the corresponding normal tissue." (PMID 40537872, 2025). "In addition, in cancer cells with defective FH, α-KG is concomitantly metabolized in both pathways: oxidative decarboxylation via the TCA cycle and reductive carboxylation via IDH2." (PMID 34829892, 2021).